AVP (arginine vasopressin)
Diseases named in the same sentence as AVP in open-access papers (continued):
Sharing a sentence is not in itself a finding about the gene and the disease.
psychiatric disorder (17 papers, 2015 to 2024). A disorder characterized by behavioral and/or psychological abnormalities, often accompanied by physical symptoms. "Numerous studies use plasma OT and AVP as mood variables to reflect central levels, and lower plasma OT and higher AVP levels are associated with various psychiatric disorders." (PMID 36569629, 2022). "These behaviors are at the very basis of more complex social behavior, and are often affected in psychiatric disorders that are associated with both ES and AVP/OXT and can be and have been reliably assessed in rodents." (PMID 31404254, 2019). "For example, lower plasma OT levels and higher AVP levels have been linked with several psychiatric disorders, including major depressive disorders and posttraumatic stress disorder, that have been characterized as involving increased amygdala activation." (PMID 27092094, 2016). "Oxytocin (OXT) and arginine vasopressin (AVP) have become promising targets for psychiatric disease treatment." (PMID 36430254, 2022). "Given the substantial sex differences in the effects of AVP and 5-HT on aggression and dominance and the dramatic sex differences seen in the incidence of psychiatric disorders, it will be important to determine the extent to which these phenomena are linked." (PMID 29184535, 2017). "The evidence on the effects of intranasal applications of OXT and AVP on clinical populations expressing a mental disorder is relatively sparse, and echoes the mixed findings for healthy population." (PMID 26858594, 2015). "Relatively few studies have been conducted on the AVP system and the relationship with altered basal blood or cerebrospinal fluid concentrations in psychiatric disorders with differences in social and moral behavior is less clear and in personality disorder, they are associated more with aggression." (PMID 38769372, 2024). "This increasingly precise understanding of how AVP systems are organized and function may ultimately lead to better therapeutic interventions for psychiatric disorders characterized by substantial social deficits." (PMID 36860367, 2023). "The understanding of how AVP systems are organized and function may ultimately lead to better therapeutic interventions for psychiatric disorders characterized by social deficits." (PMID 36860367, 2023). "However, perturbed functioning of AVP and OXT has recently been linked to a variety of mental disorders with social dysfunction, and they are suggested to have therapeutic relevance for treatment of disorders with social dysfunction as well." (PMID 31404254, 2019). "Some studies have suggested a link between AVP levels and psychiatric disorders." (PMID 26858594, 2015). "In addition, we highlight the importance of polygenic approaches for the fruitful understanding of the OXT and AVP signaling mechanisms and the studies on the effect of intranasal OXT and AVP infusions on psychiatric disorders." (PMID 26858594, 2015). "Hence, the augmented activation of the amygdala during emotional processing that is present in these psychiatric disorders may be due to decreased OT and increased AVP levels." (PMID 27092094, 2016). "Indeed, decreased or increased basal cerebrospinal or blood concentrations of AVP in psychiatric disorders are not consistent with altered moral behavior but may be more associated with levels of aggression." (PMID 38769372, 2024).
cardiovascular disease (15 papers, 2018 to 2025). "Copeptin increases rapidly in the plasma in conditions such as cardiovascular diseases, ischemic stroke, sepsis, and shock, and this increase shows that AVP release is increased and has diagnostic and prognostic value." (PMID 38223899, 2023). "Specifically, we give a description of the regulation and function of the RAS and the VPS and we focus on the mechanisms underlying the interactions of Ang II and AVP in cardiovascular regulation and on disturbances of these interactions in cardiovascular diseases." (PMID 29556787, 2018). "Since AVP is a key regulator of water balance and vascular tone, its levels are altered in various cardiovascular diseases." (PMID 40428796, 2025). "There is strong evidence that secretion of AVP and its metabolic effectiveness are significantly altered in metabolic and cardiovascular diseases." (PMID 39769071, 2024). "The secretion of AVP and other CPs is markedly influenced by changes in blood volume and pressure, as well as by other disturbances, frequently occurring in cardiovascular diseases (hypoxia, pain, stress, inflammation)." (PMID 36430892, 2022). "Regarding cardiovascular disease, evidence from human and animal research suggests that AVP has pro-atherogenic effects (e.g., encourages platelet aggregation and formation of fatty plaque in the arteries)." (PMID 32210168, 2020). "The main purpose of the present review is to draw attention to the interactions of Ang II and AVP in the regulation of the water-electrolyte balance and blood pressure in healthy individuals and in patients with cardiovascular diseases." (PMID 29556787, 2018). "Besides, it is suggested that arginine vasopressin (AVP), released from the posterior pituitary gland, may have a key role in the development of metabolic and cardiovascular disease." (PMID 32340375, 2020). "It is likely that the differences in interactions of AVP with ANS and other CPs have a significant impact on the responsiveness of the cardiovascular system to vasopressin in specific cardiovascular disorders." (PMID 36430892, 2022).
metabolic disorders (14 papers, 2015 to 2025). "Dysregulation in AVP signaling and elevated AVP levels have been linked to the development of various metabolic disorders." (PMID 40428796, 2025). "Dysregulated AVP signaling, characterized by elevated AVP or its surrogate marker copeptin, has been implicated in the development of various metabolic disorders." (PMID 40428796, 2025). "Studies on human populations revealed an association of polymorphisms of the gene encoding AVP with metabolic disorders." (PMID 39000501, 2024). "In observational and interventional studies, it has been implicated that the hydration–AVP axis is involved in the pathophysiology of metabolic diseases." (PMID 37299572, 2023). "A causal role for AVP in metabolic disorders is supported by preclinical evidence showing that high AVP concentration impairs glucose regulation in rats, an effect reversed by treatment with a selective V1aR antagonist." (PMID 32632658, 2021). "Growing evidence shows that cardiovascular and metabolic diseases, as well as inflammation and stress, are associated with an inappropriate functioning of the AVP-HPA system, and this question should be taken into consideration when pharmacological treatment is planned." (PMID 39000501, 2024). "Overall, there is convergent epidemiological evidence and a plausible mechanism for how higher circulating AVP may contribute to increased risk for metabolic disease." (PMID 32632658, 2021). "Since AVP is intrinsically regulates feeding behavior, further clarification of the underlying mechanisms of AVP on nesfatin-1/NucB2 pathway would contribute to the identification of potential therapeutic targets for the treatment of metabolic disorders in the future." (PMID 34134629, 2021). "Copeptin is a part of the precursor protein of arginine vasopressin (AVP), which regulates fluid homeostasis and the endocrine stress response and has been associated with metabolic diseases." (PMID 40142210, 2025). "Growing evidence indicates that central and peripheral interactions between AVP and steroid hormones are reprogrammed in cardiovascular and metabolic diseases and that these rearrangements exert either beneficial or harmful effects." (PMID 39000501, 2024). "Genetic epidemiology of AVP and its receptors in metabolic disorders has also been investigated in human." (PMID 33905792, 2021). "Thus, for the individual, U500 may reflect a daily water intake that is sufficient not only to meet the physiological water requirement, but also to ensure adequate urinary excretion and downregulate AVP secretion, both of which may reduce the risk of chronic renal and metabolic disease." (PMID 25866433, 2015). "Inappropriate interactions of AVP and steroids may initiate or intensify cardiovascular complications in metabolic diseases." (PMID 39000501, 2024). "A growing number of studies address the question of whether interactions between AVP and steroids are altered in metabolic diseases." (PMID 39000501, 2024). "However, the arginine-vasopressin system impairment contributes to metabolic disorders, expressing plasma copeptin changes." (PMID 36317191, 2022). "AVP may play an important role in the development of metabolic disease because it stimulates hepatic gluconeogenesis and glycogenolysis through V1aR and triggers release of both glucagon and insulin through V1bR in pancreatic islets." (PMID 32632658, 2021). "This suggests the AVP signaling may be a potent therapeutic target for management of circadian rhythm misalignment, which would also manage metabolic disorders." (PMID 33905792, 2021). "Further research should focus on clarifying the mechanisms underlying AVP’s metabolic effects and determining whether targeting AVP signaling, possibly through modulating water intake, could serve as an effective strategy for the prevention and management of metabolic diseases." (PMID 40428796, 2025).
metabolic disorders (continued). "Therefore, it is suggested that AVP corelated to a dehydrated state may play a crucial role in the development of metabolic diseases." (PMID 37299572, 2023). "Thus, strategies based on routine copeptin measurements could help to detect early metabolic disorders in progress related to AVP pathway disorders." (PMID 36317191, 2022). "Interactions between AVP and HPA are significantly altered in cardiovascular, respiratory, and metabolic diseases and during inflammation and neurogenic stress." (PMID 39000501, 2024). "The present review highlights specific mechanisms of the interactions between AVP and steroids at cellular and systemic levels and analyses the consequences of the inappropriate cooperation of various components of the AVP-HPA system for the pathogenesis of cardiovascular and metabolic diseases." (PMID 39000501, 2024).
endocrine disorder (12 papers, 2015 to 2025). "Further study on the effective role of AVP in endocrine disease confirmed that such gene may be associated with specific syndrome induced by inappropriate antidiuretic hormone secretion (SIADH), validating the co-related role of such gene in multiple pathogenesis." (PMID 29258237, 2017). "Its level of stability in the blood, quick and simple analysis, and ease of automation make it much easier to analyze than arginine vasopressin, thereby offering a suitable alternative to measuring arginine vasopressin in endocrine disorders." (PMID 37859988, 2023). "This could precede the category of exaggerated secretion of AVP in non-endocrine disorders as a sub-endocrinological disorder." (PMID 29088071, 2017).
renal disease (12 papers, 2011 to 2025). "Regardless, as evidenced by this review, there is ample evidence to suggest fructose and AVP contribute to the development of metabolic and renal disease." (PMID 35656391, 2022). "The secondary end points are differences between the two groups in systemic AVP activity, renal disease (eGFR, blood pressure, renal pain), patient adherence, acceptability and safety." (PMID 29358433, 2018). "Consequently, circulating CPP serves as a substitute for AVP in various pathological conditions, including renal diseases." (PMID 40563485, 2025). "Thus, Panel A supports the concept that renal osmolar load each day is largely influenced by diet and agrees with the dietary modification plan advanced by Amro and colleagues in 2016 (i.e., which led to reduced plasma AVP and a reduced TWI requirement for AVP reduction in kidney disease patients)." (PMID 32210168, 2020). "Water ingestion, which readily decreases circulating AVP/copeptin levels, may modify CKD progression, Studies in the 5/6 nephrectomized rat model suggested that increased water intake decreases circulating AVP levels and slows down the progression of kidney disease." (PMID 28638629, 2017).
central nervous system disorder (8 papers, 2016 to 2025). A disease involving the central nervous system. "The mechanism of AVP hypersecretion from the posterior pituitary secondary to CNS disorder is, however, not clear." (PMID 34289912, 2021).
neurological disorders (8 papers, 2013 to 2023). "Our findings may have translational value since altered OXT and AVP mechanisms in humans have been implicated in ASD and other psychiatric and neurological disorders;;;." (PMID 34687351, 2022). "To obtain further information about the proportion of NLGN4-expressing cells among AVP/OXT-producing neurons, we additionally examined PVNs and SONs in cases that had been excluded from the study owing to the presence of neurodevelopmental or neurological disorders." (PMID 36747195, 2023). "Moreover, in the present and previous studies, patients with neuroendocrine or neurological disease were excluded and non-responders tended to be younger and were not more frequently treated with drugs interfering with AVP secretion." (PMID 24223220, 2013).
neurodevelopmental disorder (6 papers, 2016 to 2022). A behavioral and cognitive disorder with onset during the developmental period that involves impaired or aberrant development of intellectual, motor, or social functions. "Studies have also shown that the neuropeptide hormones OT and arginine vasopressin (AVP) influence mammalian social and territorial behaviors and may have treatment potential for neurodevelopmental disorders." (PMID 27242401, 2016).
kidney (4 papers, 2009 to 2022). "Although we cannot definitely exclude that a hydroxyethyl-starch overload contributed at least in part to the kidney dysfunction, this issue most likely did not assume any importance for the difference between the AVP and control animals: both groups received identical colloid resuscitation." (PMID 19591694, 2009).
neurodegenerative disease (3 papers, 2015 to 2020). A disorder of the central nervous system characterized by gradual and progressive loss of neural tissue and neurologic function. "This perspective is evolving today, as described in the Introduction section above, because a growing body of epidemiological evidence consistently shows statistically significant relationships between elevated plasma AVP and increased risk of degenerative diseases." (PMID 32210168, 2020).
neuromuscular disease (2 papers, 2014 to 2019). "The AVP system is impaired in several neuromuscular diseases, suggesting that AVP may act as a physiological factor in skeletal muscle." (PMID 31461843, 2019).
respiratory disorders (2 papers, 2021 to 2024). "It has been shown that cooperation between AVP and steroid hormones may be affected by cellular stress combined with hypoxia, and by metabolic, cardiovascular, and respiratory disorders; neurogenic stress; and inflammation." (PMID 39000501, 2024). "It has also been shown that cellular stress combined with hypoxia, disturbances of metabolism, cardiovascular and respiratory disorders, neurogenic stress, and inflammation may disorganize the cooperation between AVP and steroid hormones." (PMID 39000501, 2024). "Besides disturbances of the respiratory system, elevated plasma concentrations of AVP or copeptin are found in several non-respiratory disorders that are often accompanied by abnormal respiratory patterns and increased ventilation." (PMID 34867449, 2021).
AVP also shares sentences with these, for which no sentence is quoted: Hypercalcemia (17 papers); Hypokalemia (14); pulmonary diseases (13); alcoholism (10); Ascites (7); Arrhythmia (5); head and neck cancer (5); Hypoalbuminemia (5); hypophosphatemia (5); kidney stones (5); lymphoma (5); respiratory infections (5); bipolar disorder (4); Cushing syndrome (4); Guillain-Barre syndrome (4); Hepatitis (4); injury (4); neurohypophyseal diabetes insipidus (4); olfactory neuroblastoma (4); rhabdomyolysis (4); adrenal crisis (3); bronchiolitis (3); empty sella (3); essential hypertension (3); extrapulmonary small cell carcinoma (3); Fever (3); genetic disorder (3); Hypomagnesemia (3); multiple sclerosis (3); necrotizing enterocolitis (3).
A further 224 diseases each share a sentence with AVP in 3 papers or fewer.